BCL2 (BCL2 apoptosis regulator)
Diseases named in the same sentence as BCL2 in open-access papers (continued):
Sharing a sentence is not in itself a finding about the gene and the disease.
breast carcinoma (continued). "High BCL-2 is normally associated with ER+ breast cancer and the investigation of the efficacy of ABT-199 in clinical trials focused on ER+ disease and showed a preliminary clinical benefit rate of 69%." (PMID 30720718, 2019). "Previously we demonstrated that hsa-miR-195 targets Bcl-2, it causes mitochondrial dysfunction, it induces apoptosis and augments the effect of etoposide in breast cancer cells." (PMID 30932749, 2019). "Bcl-2 positivity of breast cancers has been associated with a lower Ki-67 proliferation index, with the luminal phenotype, and especially the luminal-A phenotype." (PMID 30630524, 2019). "Bcl2 presence was positively associated with favorable prognostic features in breast cancer, emerging as an independent predictor for either DFS or OS." (PMID 31158261, 2019). "In human breast cancer, Bcl-2 positivity is also associated with a decreased risk of cancer progression and death." (PMID 30630524, 2019). "Bcl-2 is an anti-apoptotic pro-survival protein, whose expression is associated with a favorable outcome in human breast cancer." (PMID 30630524, 2019). "On the other hand, decrease or loss of Bcl-2 expression related to aggressiveness in basal cell carcinoma, and resulting in improved patient survival in human breast carcinoma." (PMID 31620453, 2019). "We show here that the BCL-2 dependency of luminal tumor cells is nevertheless mitigated by breast cancer-associated fibroblasts (bCAFs) in a manner that defines MCL-1 as another critical therapeutic target." (PMID 30631150, 2019). "The proposition to use BCL-2 inhibitors as part of the armamentarium of luminal breast cancers follows this logic, as BCL-2 expression is intrinsically associated to estrogen receptor positivity." (PMID 30631150, 2019). "Conversely, in human breast cancer, Bcl-2 positivity is associated with a lower histological grade according to numerous publications, including in locally advanced breast cancers." (PMID 30630524, 2019). "In contrast to our findings with MCL-1, BCL-2 has been shown to be a favourable prognostic marker in breast cancer, often associated with slowly proliferating low grade ER-positive tumours." (PMID 29339815, 2018). "Oleuropein treatment has caused an increase in the Bax/Bcl-2 ratio in lung cancer cells (A549), breast cancer cells and neuroblastoma cells (SH-SY5Y), in each case activating the caspase cascade causing cells to undergo apoptosis." (PMID 30004416, 2018). "Low BCL-2 expression in breast cancer has been associated with increased likelihood of recurrence and generally carries a less favorable prognosis." (PMID 30574014, 2018). "Such associations do not hold true for pro-survival BCL-2-like proteins in general and high levels of BCL-2 are actually associated with good prognosis in breast cancer." (PMID 29769323, 2018). "The miR-15/16 have been shown to suppress BCL2 in multiple cancers including gastric cancer, breast cancer, and glioma and the loss of this locus has also been observed in CLL." (PMID 29164055, 2017). "A few studies have linked breast cancer progression and drug resistance to over-expression of pro-survival factors including Bcl-2, Mcl-1 and other BH3 family members." (PMID 29099748, 2017). "The influence of expression level of anti-apoptotic protein Bcl-2 on effectiveness of apoptosis caused by PE-based immunotoxins was also reported for lymphoma cell lines and breast carcinoma cells MCF-7." (PMID 28423549, 2017). "Other studies have also demonstrated a positive association between the presence of HR-HPV and BCL2 in breast cancer and cervical cancer." (PMID 29423411, 2017).
breast carcinoma (continued). "There are several previous studies had shown that increased expression of Bcl-2 was associated with improved survival in breast cancer and probability of prognostic role in endocrine-responsive breast cancer." (PMID 27619909, 2016). "For example, Bcl-2 expression in cancer cells is associated with liver metastasis in colorectal cancer, lymphovascular invasion of breast cancer cells, and nodal metastasis and invasion in laryngeal squamous cell carcinoma." (PMID 26621844, 2016). "To determine the mechanism underlying 5-FU-induced alteration of BAX and Bcl-2 genes, we conducted RT-PCR analysis of breast cancer cells after serial diluted 5-FU treatment (0.5, 1.0, and 5.0 μg/ml), and total RNA was extracted at 3, 6, 9, and 24 h." (PMID 26716512, 2016). "Contrary to expectations, high apoptotic index is significantly associated to poor prognosis while high BCL2 expression correlates to good prognosis of breast cancer patients." (PMID 27746811, 2016). "Bcl-2 is an antiapoptotic protein that is a key regulator of apoptosis and associated with low-grade, slowly proliferating, ER+ breast cancer." (PMID 26840298, 2016). "The favorable prognosis previously associated with Bcl-2-positive breast cancer probably reflects the indirect effect of frequently coexpressed hormone receptors and adjuvant endocrine therapy." (PMID 26472348, 2015). "Hsp90 is implicated in increasing the survival of breast cancer cells by stabilising oncogenic proteins including Bcl-2, and if targeted, can allow tumour cells to overcome apoptotic resistance through Hsp90-Bcl-2 interactions." (PMID 26416415, 2015). "Apoptosis was also induced in MCF-7 breast cancer cells by 150 μM quercetin and it was associated with decreased levels of Bcl-2, reduced mitochondrial membrane potential and enhanced level of activated caspase-6, -8, -9." (PMID 26694341, 2015). "Altered expression of the Bcl-2 family of proteins: Bax and Bcl-2 resulting in changing the Bcl-2/Bax ratio is frequently implicated in breast cancers and is often associated with poor survival." (PMID 26499490, 2015). "In breast cancer cells, hypermethylation of the second exon of antiapoptotic factor BCL-2 has been found associated with its diminished expression." (PMID 25606572, 2014). "Further ST caused cell death involves the induction of apoptosis in breast cancer cells via mitochondrial membrane depolarization and increase in Bax/Bcl-2 ratio." (PMID 24160369, 2013). "Immunohistochemical analysis of human primary breast cancers revealed that a comparatively large proportion of ILBCs lack BCL2 expression, despite complete loss of E-cadherin." (PMID 24023670, 2013). "In breast cancer, loss of BCL2 has repeatedly been associated with high grade tumors and other aggressive carcinoma entities, which shows that BCL2 acts as a differentiation marker in the mammary gland." (PMID 24023670, 2013). "Although there are now a large number of studies focusing on Bcl-2 expression in breast cancers, however, the association between its expression and chemosensitivity was not conclusive, mostly due to the small sample size of each study." (PMID 24370277, 2013). "In this study higher BCL2 expression was significantly associated with improved survival from breast cancer (p = 0.015), in keeping with previous reports." (PMID 23961365, 2012). "The effect of SNP genotype on tumour BCL2 protein levels and breast cancer susceptibility was assessed by logistic regression." (PMID 23961365, 2012). "We also confirmed the known association between high levels of tumour BCL2 and improved survival from breast cancer." (PMID 23961365, 2012).
breast carcinoma (continued). "Many studies have clearly demonstrated that increased BCL2 expression is associated with improved outcome from breast cancer." (PMID 23961365, 2012). "In conclusion, we found that higher tumour BCL2 expression is associated with improved survival from breast cancer, in keeping with previous studies." (PMID 23961365, 2012). "The data presented here are consistent with previous reports that show that in breast cancer, in contrast to non-Hodgkins lymphoma, higher tumour protein expression of BCL2 is associated with improved survival." (PMID 23961365, 2012). "In the logistic regression model, BCL-2 SNP938 variant genotype CC was associated with a decreased risk for breast cancer by 0.40-fold compared with the homozygote AA." (PMID 21457555, 2011). "BCL-2 (B-cell leukemia/lymphoma 2) gene has been demonstrated to be associated with breast cancer development and a single nucleotide polymorphism (SNP; -938C > A) has been identified recently." (PMID 21457555, 2011). "AA genotype of BCL-2 (-938C > A) is associated with susceptibility of breast cancer, and this genotype is only associated with the nodal status and pathological diagnosis of breast cancer." (PMID 21457555, 2011). "In contrast, we showed that allele A was associated with low Bcl-2 expression in breast cancer cell lines and AA genotype is in positive relation to breast cancer susceptibility." (PMID 21457555, 2011). "We found that homozygous AA genotype was associated with an increased risk (AA vs AC+CC) by 2.37-fold for breast cancer development and significant association was observed between nodal status and different genotypes of BCL-2 (-938C > A) (p = 0.014)." (PMID 21457555, 2011). "We further investigated the possible linkage of BCL-2 (-938C > A) polymorphism with Bcl-2 expression level in vitro; we tested the genotypes of the polymorphism and Bcl-2 expression in 4 breast cancer cell lines." (PMID 21457555, 2011). "The result of western blot analysis indicated that allele A was associated with the lower level of Bcl-2 expression in breast cancer cell lines." (PMID 21457555, 2011). "Studies confirmed that antisense oligonucleotide of BCL-2 can effectively reduce the expression of BCL-2 in breast cancer cells, reduced the inhibition caused by the BCL-2 gene in chemotherapy-induced apoptosis, improved the treatment effect." (PMID 20691103, 2010). "We show that the overexpression of BCL-W and BCL2 is linked to determining cell fate through autophagy in ICI resistant breast cancer models." (PMID 20062536, 2010). "In contrast to non-Hodgkin's lymphoma, BCL2 protein expression in breast cancer is associated with an indolent phenotype of low-grade, slowly proliferating, ER+ breast tumours." (PMID 20664598, 2010). "We conclude that the co-inhibition of BCL-W and BCL2 restores sensitivity in antiestrogen-resistant breast cancer cells by promoting an autophagy-associated increase in necrosis." (PMID 20062536, 2010). "Previous studies had identified that expression of BCL2 was associated with improved survival from breast cancer, but this was attributed to its correlation with ER status." (PMID 20664598, 2010). "Paradoxically, expression of Bcl-2 has been consistently associated with a better prognosis of breast cancer patients." (PMID 20969773, 2010). "Immunohistochemical staining studies suggested that Bcl-2 expression is linked to hormonal regulation in human breast cancers." (PMID 18652667, 2008). "ER transcriptional activity results in Bcl-2 upregulation in breast cancer, and both ER and Bcl-2 are associated with chemotherapy resistance in breast cancer." (PMID 18430249, 2008). "The published data incorporating 5,892 cases strongly support the prognostic role of BCL2 as assessed by IHC in breast cancer showing that it is associated with both DFS and OS (pooled HR estimates of 1.66 and 1.64 respectively)." (PMID 18510726, 2008).
breast carcinoma (continued). "This 50-set also contains genes previously linked to breast cancer prognosis, metastasis or treatment response (BCL2, CXCL12 and FBLN1)." (PMID 19094230, 2008). "Breast cancer studies in the literature have consistently demonstrated an association between high Bcl-2 expression and improved survival, and similar findings have been demonstrated in other diseases." (PMID 18430249, 2008). "Although Bcl-2 is an anti-apoptotic protein, high Bcl-2 expression has been observed in ER-positive breast cancers, as well as in progesterone receptor (PR)-positive breast cancers, and has been associated with improved survival in breast cancer." (PMID 18430249, 2008). "Wilms' Tumor 1 protein has been associated with aggressive phenotypes of breast cancer and was recently shown to upregulate bcl-2 expression in BT-474 breast cancer cells." (PMID 17854498, 2007). "In vitro drug response assays showed Bcl-2-negative breast cancers to be more susceptible to chemotherapeutic drugs than bcl-2-positive, but immunohistochemical studies of breast cancers have been less conclusive." (PMID 17285125, 2007). "A decreased expression of Bcl-2 protein was shown to be associated with a poor clinical outcome in various human cancers including breast cancer." (PMID 16839413, 2006). "Bcl-2 overexpression in human breast cancer is reported to be associated with the presence of estrogen receptors (ER), small tumor size, low tumor grade, and a favorable prognosis, despite contradictory results." (PMID 16911782, 2006). "Bcl-2 expression was associated with favourable prognosis in breast cancer and was both estrogen receptor(ER) and progesterone receptor (PR) associated." (PMID 17092354, 2006). "Clinical studies have shown that Bcl-2 expression with loss of apoptosis are important determinants of lymph node metastasis in breast cancer." (PMID 14612905, 2003). "In this study we show for the first time that treatment of breast cancer cells with ZOL is associated with release of mitochondrial cytochrome c into the cytosol consistent with a decrease in the action of bcl-2." (PMID 11986784, 2002). "In the breast carcinoma MX-1, hypersensitive to cisplatin and to the lonidamine+cisplatin combination, the efficacy of drug treatment was associated with phosphorylation of bcl-2 followed by down-regulation of the protein." (PMID 9472640, 1998). "In breast cancer, miR-21 has been associated with apoptosis via B-cell lymphoma 2 (BCL2)." (PMID 39335585, 2024). "Given that hsa-miR-96 is known as a candidate diagnostic marker in breast cancer, its potential role in regulating BCL2 could be significant in drug resistance within HER2-positive breast cancer." (PMID 39682150, 2024). "High Bcl-2 is associated with better breast cancer outcomes." (PMID 37370761, 2023). "These compounds involve the linoleic acid derivatives jasmonic and corchorifatty acids previously shown to stimulate the mitochondrial apoptotic pathway that is tightly associated with the expression ratio of Bax/Bcl2, an index that was shown to be upregulated in ScBEE-treated breast cancer cells." (PMID 36771614, 2023). "This led to reduced metabolic activity and cell adherences associated with elevated expression of pro-apoptotic genes (BCL-2, caspase 3) in 4T1 breast cancer cells in vitro exposed to alternating current magnetic field (ACMF) compared to MENs-DOX without field exposure." (PMID 37845238, 2023).
breast carcinoma (continued). "Pachymaran can lead to the imbalance of (B-cell lymphoma-2 (Bcl-2)/Bcl2-associated X (Bax) by regulating the ratio of Bcl-2/Bax protein, inhibits the growth of tumor cells and induces apoptosis of human breast cancer cells by activating apoptosis signaling pathway." (PMID 37838763, 2023). "However, clinical and preclinical studies have revealed that pharmacological inhibition of Bcl-2 and Bcl-xL alone in breast cancer cells causes the induction of Mcl1, which then leads to drug resistance and failure to inhibit tumor growth." (PMID 36853387, 2023). "Interestingly, in breast cancer, the overexpression of Bcl-2 has been linked with the low-grade, slow-proliferating ER+ type and was associated with favorable outcomes." (PMID 35053443, 2022). "However, research in breast cancer cells has revealed that miR-21 expression is inversely associated with Bcl-2 expression, which is fundamentally different from restenosis vascular smooth muscle cells." (PMID 36082081, 2022). "High level expression of BCL2 in breast cancer is associated with a better prognosis." (PMID 33452364, 2021). "The paradox of low BCL2 levels associated with a bad prognosis in breast cancer could be related to Beclin-1 inhibition." (PMID 33452364, 2021). "The significant association between bcl-2 (protein) and Luminal B might lead to reduced susceptibility to anti-ER therapy by breast cancer cases in our region." (PMID 34188682, 2021). "As low BCL2 expression is associated with unfavorable clinical outcomes, more active adjuvant treatment might be recommended for breast cancer patients with low BCL2 expression." (PMID 34099764, 2021). "The correlation of BCL2 with estrogen sensitivity may be the underlying reason for the relatively high survival rates of BCL2+ breast cancer patients." (PMID 34441794, 2021). "Moreover, our data also signify that these compounds stimulate apoptosis, particularly in HER2-positive breast cancer cells, which is associated with the Bcl-2/Bax/caspase-3 signaling pathway." (PMID 34502529, 2021). "BCL-2 overexpression is found to be associated with different types of cancers such as prostate cancer, chronic lymphocytic leukemia, non-small cell lung cancer, breast cancer, esophageal cancer, lung cancer, and endometrial cancer." (PMID 33708254, 2021). "Nar was revealed to induce apoptosis of breast cancer cells; hence, the expression of different apoptosis-associated genes including Bcl-2 and Bax were analyzed in order to achieve a better understanding of how Nar exerts cytotoxic influence and induces apoptosis." (PMID 33680016, 2020). "Bcl-2 expression in cancer patient samples is also associated with cancer progression, including liver metastatization in colorectal cancer, lymphovascular invasion of breast cancer and gastric cancer staging." (PMID 32455818, 2020). "One of the early attempts to investigate the correlation between p21 and bcl2 SNPs with susceptibility to breast cancer showed that p21 was more commonly expressed in breast cancer patients and bcl2 polymorphism was likely to be associated with breast cancer risk." (PMID 32711446, 2020). "Bcl-2 positivity has also been associated with longer disease-free survival, longer overall survival, and lower risk of cancer-related death in other reports, especially in luminal breast cancers." (PMID 30630524, 2019).